IL1B (interleukin 1 beta)
Diseases named in the same sentence as IL1B in open-access papers (continued):
Sharing a sentence is not in itself a finding about the gene and the disease.
depression (continued). "Depressive disorders is characterized by inflammation, as indicated by elevated concentrations of pro-inflammatory cytokines (e.g., IL-1β, IL-2, and IL-6), and it is characterized by cell-mediated immune (CMI) activation and Th1-like response, as suggested by increased production of IFN-γ." (PMID 31215856, 2020). "IL-1β has shown to decrease neurogenesis in vitro in human hippocampal progenitor cells, a common finding in depression, via activation of the kynurenine pathway; this effect being partially rescued by both inhibitors of this pathway and traditional antidepressants." (PMID 31379879, 2019). "Furthermore, elevated serum levels of several pro-inflammatory cytokines, such as TNFα, IL-1β, and IL-6, have also been detected in patients with depression." (PMID 31312123, 2019). "A majority of the clinical data reported increases in IL-1β levels in depressed patients in the periphery and identified a role of this cytokine in response to treatment with antidepressants, as well as a possible marker of depression." (PMID 30610610, 2019). "Indeed, NLRP3 gene expression was found elevated in PBMCs of patients with major depression corresponding with elevated serum levels of IL-1β and IL-18, supporting the clinical applicability of inflammasome activation in depression." (PMID 31749681, 2019). "When considering the link between IL-1β and depression, the results have been mixed." (PMID 30967802, 2019). "This phenomenon suggests that IL-1β plays a key role in the pathogenesis of depression." (PMID 29343269, 2018). "Next, we used RNA interference (RNAi) to reduce (knock down) IL-1β protein as a means to determine whether a down-regulation or blockade of IL-1β function within the vmPFC would reverse depression phenotypes." (PMID 30666189, 2018). "It has been speculated that depression is related to an increased secretion of cytokines, in particular IL-1β, by macrophages." (PMID 29343269, 2018). "Collectively, these findings reveal that curcumin protects against IL-1β-induced neuronal apoptosis, which may be related to the display of depression-like behaviors in stressed rats." (PMID 30666189, 2018). "Moreover, only IL-1β was subjected to further investigation and analysis in this depression animal model, and the analysis of other pro-inflammatory factors would also be valuable." (PMID 30666189, 2018). "Moreover, IL-1β reduces neurogenesis in the hippocampus—another well-characterized event that occurs in depression." (PMID 30662368, 2018). "Therefore, the concentrations of cytokines, including IL-1α, IL-1β, and IL-6, were detected by ELISA kits in the serum of mice with restraint stress-induced anxiety and depression." (PMID 30400578, 2018). "Furthermore, in chronic mild stress (CMS) model of depression, the concentrations of IL-1β, IL-6, IL-18 and TNF-a in the brain or serum were enhanced." (PMID 30390665, 2018). "For example, melancholia is characterized by increased levels of acute phase proteins, e.g., haptoglobin, expression of T cell activation markers and increased resistance of IL-1β and sIL-2R production to dexamethasone administration as compared to simple major depression." (PMID 29103192, 2018). "Meanwhile, a large body of evidence has been collected to support that P2X7 receptor may be pivotal in depression and mediates the IL-1β maturation." (PMID 30483062, 2018). "In addition, higher IL-1β and TNF-α levels were associated with higher Hamilton Depression Rating Scale (HAMD) scores, while higher IL-8 levels were associated with lower HAMD and Hamilton Anxiety Rating Scale scores." (PMID 29856741, 2018). "This overexpression of IL-1β may indicate one potential pathway through which neuroinflammatory mechanisms may proceed to produce neuronal apoptosis, eventually leading to depression." (PMID 30666189, 2018).
depression (continued). "In order to determine whether curcumin protects against IL-1β-induced neuronal apoptosis, we infused IL-1β-expressing viruses into the vmPFC of unstressed rats to overexpress IL-1β and examined the effects on neuronal apoptosis and depression-like behaviors." (PMID 30666189, 2018). "Another study found that XPJY has the better effect on improving learning and memory ability in depression rats than sertraline, which might he related to reduce the inflammatory factors level, such as IL-1β, IL-6 and TNF-α, in serum and hippocampus." (PMID 28118829, 2017). "Further, stress induces IL-1β in the hippocampus, which decreases neurogenesis and contributes to depression, while inhibition of IL-1β blocks stress-induced decreases in neurogenesis and depression-like behavior." (PMID 28210782, 2017). "Our earlier studies have shown that learning and memory ability in depression rats might be related to reduce the inflammatory factors level, such as IL-1β, IL-6 and TNF-α, in serum and hippocampus." (PMID 28118829, 2017). "Hence, this indicates that IL-1β is essential in depression in terms of the development of depressive symptomology and neurogenesis impairment." (PMID 29049348, 2017). "Moreover, we also used FST and SPT to demonstrate the depression-like behaviors produced by the LPS alone or in combination with the IL-1β shRNA in mice." (PMID 28931410, 2017). "Hippocampal tissue inflammation and, particularly, enhanced interleukin-1β (IL-1β) signaling may contribute to depression." (PMID 28486969, 2017). "We evaluated whether IL-1β knock-down induced by lentivirus in the hippocampus shows memory enhancing, anti-depression, and anxiolytic effects in the background of acute neuroinflammation induced by LPS in mice." (PMID 28931410, 2017). "In addition, this is also the first study showing the role of serum IL-1β and IL-6 in the individual differences of ketamine’s antidepressant response in the comorbidity of neuropahtic pain and depression in rodents." (PMID 28600519, 2017). "The human IL1B gene (interleukin 1β) has an SNP marker (rs1143627) of a wide variety of human diseases such as Graves’ disease, major recurrent depression, greater body fat in older men, non–small cell lung cancer, hepatocellular carcinoma, gastric cancer, gastric ulcer, and chronic gastritis." (PMID 28105927, 2016). "Similar to the current results, in animal models of sickness behavior, prolonged production of TNF-α, IL-6, and IL-1β can also lead to a variety of symptoms including fat and muscle wasting and behavioral changes similar to symptoms of depression that also occur in cancer patients." (PMID 25945105, 2015). "Additional subgroup analysis on those with baseline CES-D scores greater than 16 (suggesting depression) further implicated a role for IL-1β in depression as levels were shown to be 73 % higher than in those with CES-D scores indicating a lack of depression." (PMID 26545369, 2015). "Numerous studies have reported that circulating pro-inflammatory cytokines, such as interleukin-1 beta (IL-1β), IL-6, interferon gamma (IFN-γ), and tumor necrosis factor alpha (TNF-α), may be associated with some forms of major depression." (PMID 26521132, 2015). "A biobehavioral interaction model was used to guide this study, providing an overview of the relationships among psychosocial (stress, depression, loneliness, religious coping, and spiritual pain) and biological factors (cortisol and IL-1β), and health outcomes." (PMID 27417804, 2015). "As the change in the KYN/TRP ratio was also significantly correlated with the change in CES-D scores, it may be possible that IL-1β influenced depression via such IDO-related mechanisms." (PMID 26545369, 2015). "Aggregate data from the 15 studies on IL-1β did not convincingly confirm or refute an association with major depression." (PMID 26065825, 2015).
depression (continued). "As hypothesized, interactive effects were revealed at loci in IL6 and IL1β that accounted for differences in depressive symptoms, over and above the contributions of maternal depression history, earlier depressive symptoms, gender, and asthma diagnosis." (PMID 25596176, 2015). "Like stressors, which may engender features of depressive disorder in rodents, the systemic administration of proinflammatory cytokines such as interleukin-1β (IL-1β) and tumor-necrosis factor-α (TNF-α) increases hypothalamic-pituitary-adrenal (HPA) activity." (PMID 26417153, 2015). "Interestingly, depression was also proved to be associated with the increased inflammatory response involving a higher level of IFN-γ, IL-1β, TNF-α, IL-6, and IL-1 and decreased IL-10." (PMID 24744682, 2014). "Correlation analysis between HADS score and cytokine levels revealed a positive association of anxiety and/or depression with IL-1β, IL-6, IL-8, and TNF-α and a negative correlation with IL-10." (PMID 25309921, 2014). "In addition, the elevated levels of pro-inflammatory cytokines (e.g., IL-6 and IL-1β) can induce symptoms of a syndrome termed “sickness behavior”, which include depression, reduction in locomotor activity, anhedonia, anorexia and cognitive disturbances." (PMID 25514226, 2014). "It is interesting that those peripheral cytokines that predict emergence of depression after a stroke (e.g., IL-18) differ from the key cytokines typically implicated in depressive illnesses that occur in other circumstances (e.g., IL-6, TNF-α, or IL-1β)." (PMID 23675319, 2013). "It has been demonstrated that omega-3 fatty acids may modify depression symptoms by inhibiting proinflammatory cytokines, particularly IL-1β and TNFα." (PMID 21864357, 2011). "Indeed, elevated levels of circulating pro-inflammatory cytokines, including TNFα, IL-6 and IL-1β, are frequently observed in patients with depression." (PMID 21306618, 2011). "Central and systemic administration of proinflammatory cytokines (IL-1β, TNF-α, IL-6) to animals induces what has been described as “sickness behavior,” which is characterized by many of the physiological and behavioral changes associated with depression." (PMID 20029634, 2009). "Cytokines like IL-1β are suggested to be involved in the pathophysiology of depression, and excessive secretion of macrophage cytokines (IL-1β, tumor necrosis factor-α, interferon-γ could be a potential causative factor." (PMID 20029625, 2009). "Patients with depression exhibit significant inflammatory characteristics, particularly in peripheral blood, where levels of inflammation-related factors and their receptors, such as IL-1β, IFN-γ, chemokines (e.g., CCL2, CXCL4, CXCL7), and other inflammatory mediators, are markedly elevated." (PMID 41601490, 2026). "Furthermore, growing evidence suggests that individuals with depression also exhibit elevated levels of circulating cytokines like IL-6, IL-1β, TNF-α, IFN-α, prostaglandin E2 (PGE2), and chemokine CCL2, as well as acute-phase proteins such as C-reactive protein (CRP)." (PMID 40573262, 2025). "In addition, in some animal models of depression, brain IL-1β expression was increased and treatments with IL-1ra, deletion of IL-1R1, or inhibition of inflammasome activities, required for the production of active IL-1β, have been shown to reduce depressive-like behaviors." (PMID 40703575, 2025). "Furthermore, the combined use of probiotics (Bifidobacterium and Lactobacillus) has been found to decrease the incidence of post-stroke depression and lower serum inflammatory markers, such as nuclear factor kappa-light-chain-enhancer of activated B cells (NF-κB) and interleukin-1 beta (IL-1β)." (PMID 40625834, 2025). "In depression, deficiency of Kir6.1 activates the NLRP3 inflammasome through excessive accumulation of mitochondrial ROS, triggering caspase-1-dependent cleavage of gasdermin D (GSDMD), leading to astrocyte pyroptosis and the release of the pro-inflammatory cytokine IL-1β." (PMID 40936908, 2025).
depression (continued). "In rodent models of diabetes-associated depression, activation of indoleamine 2,3-dioxygenase (IDO)—a key enzyme in tryptophan metabolism—results in decreased hippocampal serotonin (5-HT) levels and elevated pro-inflammatory cytokines such as TNF-α, IL-1β, and IL-6." (PMID 41299994, 2025). "In addition to IL-1B, IL-6 is of particular importance in the study of depression." (PMID 40313235, 2025). "Furthermore, the sustained activation of the cGAS-STING pathway can also increase the production of ROS, leading to more mtDNA release, which further drives the secretion of IL-1β and IL-18 and affects ATP synthesis, impacting mitochondrial energy metabolism and mediating the onset of depression." (PMID 40699781, 2025). "Depression, a pervasive mental health condition, has increasingly been linked to neuroinflammation, as evidenced by elevated levels of pro‐inflammatory markers such as TNF‐α and IL‐1β observed in patients, which underscores the role of inflammation in its pathophysiology." (PMID 40171943, 2025). "Interestingly, even in human blood, cumulative meta-analysis revealed that there is no consistent association with IL-1β and TNFα whilst IL-6 showed significance with depression in humans." (PMID 40179065, 2025). "In addition, retinal injury may initiate hippocampal microglial activation via the NLRP3/IL-1β pathway, leading to neuroinflammation and subsequent depression-like behavior." (PMID 40936908, 2025). "The activation of IL-1β signaling pathways may disrupt neurotransmitter systems, impair neuroplasticity, and contribute to the cognitive deficits often observed in people with depression." (PMID 40305200, 2025). "Additionally, emerging literature suggests that functional allelic variants of genes for IL-1β and TNF-α, as well as genes critical for T-cell function, may increase the risk of depression and be associated with a reduced response to antidepressant therapy." (PMID 39595067, 2024). "The P2X7R/NLRP3/IL‐1β signaling pathway may play an important role in the antidepressant‐like behavior of taVNS, which provides a promising mechanism for taVNS clinical treatment of diabetes combined with depression." (PMID 38752512, 2024). "TLR4-NF-κB/NLRP3/ IL-1β pathway may be a key signaling pathway in depression." (PMID 38459460, 2024). "It was found that the level of BDNF protein in the hippocampus was significantly up-regulated, and the levels of NF-κB, NLRP3, and IL-1β were significantly decreased, suggesting that salidroside may ameliorate depression by inhibiting the NF-κB/NLRP3 signaling pathway." (PMID 39770545, 2024). "This oxidative stress and increased depression lead to demyelination and cerebral atrophy, accompanied by elevated concentrations of inflammatory mediators such as tumor necrosis factor (TNFα) and specifically interleukin IL-6, along with IL-1α and IL-1β, in the serum and CSF." (PMID 37693246, 2023). "Furthermore, polymorphisms in the IL-1β, TNF-α, and C-reactive protein may increase the risk of depression, and single nucleotide polymorphisms (SNP) in the IL-1β, IL-6, and IL-11 genes may be associated with decreased efficacy of anti-depressant treatment." (PMID 36768580, 2023). "The cytokine hypothesis suggests that in depression, the number of pro-inflammatory cytokines such as IL-6, IL-1β and TNF-α is increased, while the number of anti-inflammatory cytokines such as IL-10 and TGF-β is decreased, tilting the overall immune response toward inflammation." (PMID 37387537, 2023). "Interestingly, ZW inhibited diabetes-induced anxiety and depression by minimizing the neuroinflammatory response by decreasing NfκB, IL-1β, and IL6 mRNA levels and the number of TNF-α- and GFAP-immunostained neurons and serum level of TNF-α and CRP because of its antioxidant power." (PMID 38105928, 2023).
depression (continued). "There is evidence that depressive disorder is characterized by increased activity of immune cells and increased levels of proinflammatory cytokines, especially pivotal cytokines such as interleukin (IL)-1β, IL-6, tumor necrosis factor (TNF)-α, and interferon (IFN)-γ." (PMID 37834806, 2023). "However, we acknowledge the differences in our statistical approach (univariate versus multi-variate), larger sample sizes in our IL-1β moderator analysis, and our mixed sample of anxiety and depression as potential reasons for the deviation when comparing our findings." (PMID 35880170, 2022). "However, this could only be shown, probably due to variance issues, when the TNF-α distribution was dichotomized by a median split, although TNF-α and IL-1β shared 31% of the variance in the group with depression." (PMID 36261698, 2022). "Furthermore, IL-6, tumor necrosis factor-alpha (TNF-α), and IL-1β are implicated in the pathophysiology of depression, and individuals with depression often have elevated circulating IL-1β, IL-6, and TNF with reduced levels of interferon-gamma (IFN-γ), IL-10, and IL-4." (PMID 35546876, 2022). "A recent study investigated associations between levels of six cytokines (IL-1β, eotaxin, IL-15, IL-6, TNF-α, and leptin) and chronic multisite pain (CMP) in a sample of people living with HIV, but also incorporated PHQ-9 scores as a measure of depression in their regression models." (PMID 35618889, 2022). "IL-1β, a pro-inflammatory cytokine is described in the context of psychiatric conditions, such as depression ⁠ and schizophrenia, where it may predict a severity of general and global symptomatology or ASD the features of which are especially present in PWS patients." (PMID 32495042, 2021). "As IL-1β and iNOS released by microglia help amplify neuroinflammation in depression and subsequently lead to neurotoxicity and pathological changes, this finding suggests that IL-1β and iNOS in the hippocampus may play an important role in the processes of microglial activation." (PMID 34489395, 2021). "As we noted in the results, the evaluated IL-1β was specifically found in depressive patients, these findings thus indicate that the inflammatory process might interact with the brain changes, and then contribute significantly to the development of depression." (PMID 34900691, 2021). "Finally, we determined whether EA at bilateral Dachangshu (BL25) regulates the expression of P2Y12 in the mPFC and then inhibits the activation of microglia and the expression of IL-1β in the mPFC, thereby alleviating visceral pain and depression in IBD mice." (PMID 34930362, 2021). "In addition, the IL-1β level has been suggested to be related to treatment-refractory depression." (PMID 34576215, 2021). "Therefore, IL-1β may regulate serotonin metabolisms, which may be involved in progression of depression." (PMID 33790733, 2021). "Moreover, TNF-α and IL-1β may bind with the peripheral afferent nerve fibers, which in turn stimulate ascending catecholaminergic fibers in the brain to affect depression." (PMID 34827513, 2021). "The increased level of proinflammatory cytokines such as IL-1β, IL-6, and IFN-γ that found in the peripheral circulation and hippocampus of depressive patients has been shown contributing to the development of depression-like behaviors in animal models with estrogen deficiency." (PMID 35155523, 2021). "However, whether IL-1β expression-suppressing probiotics can simultaneously alleviate cognitive impairment and depression remains unclear." (PMID 33182607, 2020). "In a mouse model of depression induced by a strong pathogen lipopolysaccharide (LPS), the expression of Toll-like receptor 2 in microglia was evidently increased, while RNA levels of neuroinflammatory factors, such as IL-1β and IL-6, in the cortex and hippocampus were significantly enhanced." (PMID 33192466, 2020).